FAM47B (family with sequence similarity 47 member B)
Synonyms: FLJ35782
Tractability: No criterion of Open Targets' tractability assessment is met for any kind of drug.
Gene: Protein-coding gene on chromosome X (34,942,796 to 34,944,915, forward strand). Ensembl gene ENSG00000189132.
Gene Ontology:
Molecular function: protein binding
Homologues: Orthologues: chimpanzee FAM47B (95% identical), macaque FAM47B (80% identical), Drosophila melanogaster Frl (16% identical), Caenorhabditis elegans frl-1 (14% identical), Caenorhabditis elegans daam-1 (13% identical), zebrafish fmn2b (12% identical), Drosophila melanogaster dia (12% identical), Caenorhabditis elegans fhod-1 (11% identical), Caenorhabditis elegans exc-6 (11% identical), Drosophila melanogaster capu (11% identical), Drosophila melanogaster form3 (11% identical), Caenorhabditis elegans cyk-1 (10% identical), and 2 more. Paralogues in human: FAM47C (75% identical), FAM47A (67% identical), FMNL2 (17% identical), FMNL1 (17% identical), DIAPH1 (16% identical), FMNL3 (16% identical), DIAPH2 (15% identical), DIAPH3 (15% identical), INF2 (15% identical), DAAM1 (14% identical), DAAM2 (14% identical), FMN2 (14% identical), and 6 more.
Diseases named in the same sentence as FAM47B in open-access papers:
FAM47B is named in the same sentence as 2 diseases in open-access papers, as found by Europe PMC text mining. Sharing a sentence is not in itself a finding about the gene and the disease.
FAM47B shares sentences with these, for which no sentence is quoted: Infertility (1 paper); tumor (1).